SQLE-DT (SQLE divergent transcript)
Synonyms: lnc030
Gene: Long non-coding RNA gene on chromosome 8 (124,996,982 to 124,998,286, reverse strand). Ensembl gene ENSG00000253513.
Diseases named in the same sentence as SQLE-DT in open-access papers:
SQLE-DT is named in the same sentence as 4 diseases in open-access papers, as found by Europe PMC text mining. Sharing a sentence is not in itself a finding about the gene and the disease.
SQLE-DT shares sentences with these, for which no sentence is quoted: breast cancer (3 papers); breast tumor (1); cancer (1); tumor (1).